TM6SF1 (transmembrane 6 superfamily member 1)
Description:
May function as sterol isomerase.
Tractability: Antibody: UniProt predicts a signal peptide or a membrane-spanning region. PROTAC: ubiquitination databases record sites on it.
Gene: Protein-coding gene on chromosome 15 (83,107,454 to 83,144,854, forward strand). Ensembl gene ENSG00000136404.
Subcellular location: Lysosome membrane
Gene Ontology:
Cellular component: lysosomal membrane
Genetic constraint (gnomAD): Loss-of-function variants: 32 observed, 33.87 expected, observed/expected ratio (o/e) 0.94, 90% interval 0.71 to 1.27. The upper end of that interval is the gene's LOEUF score, 1.27, which puts it in group 5 of 6, group 1 being the genes least tolerant of losing a copy. Missense variants: 353 observed, 410.16 expected, observed/expected ratio (o/e) 0.86, 90% interval 0.79 to 0.94. Synonymous variants: 161 observed, 155.42 expected, observed/expected ratio (o/e) 1.04, 90% interval 0.91 to 1.18.
Homologues: Orthologues: chimpanzee TM6SF1 (100% identical), dog TM6SF1 (96% identical), pig TM6SF1 (96% identical), mouse Tm6sf1 (94% identical), macaque TM6SF1 (93% identical), guinea pig TM6SF1 (88% identical), rabbit TM6SF1 (86% identical), rat Tm6sf1 (81% identical), tropical clawed frog tm6sf1 (68% identical). Paralogues in human: TM6SF2 (50% identical).
Diseases named in the same sentence as TM6SF1 in open-access papers:
TM6SF1 is named in the same sentence as 7 diseases in open-access papers, as found by Europe PMC text mining. Sharing a sentence is not in itself a finding about the gene and the disease. The quoted sentences say what the papers report.
breast carcinoma (3 papers, 2016 to 2021). "TM6SF1, transmembrane 6 Superfamily Member 1, has been found to be a DNA promoter hypermethylation marker in breast cancer." (PMID 34540825, 2021). "Studies have shown that the methylation level of TM6SF1 gene in breast cancer patients’ cancer tissues and breast milk is significantly higher than that in healthy people." (PMID 32751923, 2020).
lung carcinoma (2 papers, 2022). "However, limited research has been carried out regarding the role of TM6SF1 in tumorigenesis and cancer progression, and comprehensive examinations of its biological functions in lung cancer are necessary." (PMID 35620733, 2022).
colon adenocarcinoma (1 paper, 2021). "A cluster of 13 CpG loci (11 genes) were identified that displayed differential methylation in colon adenocarcinoma (COAD) (N = 289) compared to normal colon tissues (N = 38): ZNF671, TWIST1 (two CpG loci), TMEFF2, TM6SF1, GAS7, MAL, HIN1 (two CpG loci; SCGB3A1), COL6A2, AKR1B1, GPX7, ARHGEF7)." (PMID 34903270, 2021).
liver cancer (1 paper, 2020). An epithelial or non-epithelial malignant neoplasm that arises from the liver. "Hypermethylation of TM6SF1 gene also appears in HBV-related liver cancer." (PMID 32751923, 2020).
cancer (6 papers, 2011 to 2024). A tumor composed of atypical neoplastic, often pleomorphic cells that invade other tissues. "Specifically, increases in methylated AKR1B1, HIST1H3C and TM6SF1 during treatment were found to be correlated with a higher Residual Cancer Burden (RCB)." (PMID 38245552, 2024).
tumor (2 papers, 2022 to 2023). "Zhong and their colleagues revealed that the TM6SF1 was related to the NSCLC tumor Microenvironment." (PMID 36591493, 2022).
TM6SF1 also shares sentences with these, for which no sentence is quoted: diabetes (1 paper).